CT47A11 (cancer/testis antigen family 47 member A11)
Synonyms: CT47.11
Gene: Protein-coding gene on chromosome X (120,933,840 to 120,937,158, reverse strand). Ensembl gene ENSG00000226929.
Subcellular location (Human Protein Atlas): Nucleoli
Homologues: Orthologues: macaque CT47B1 (77% identical). Paralogues in human: CT47A1 (100% identical), CT47A10 (100% identical), CT47A12 (100% identical), CT47A2 (100% identical), CT47A3 (100% identical), CT47A4 (100% identical), CT47A5 (100% identical), CT47A6 (100% identical), CT47A7 (100% identical), CT47A8 (100% identical), CT47A9 (100% identical), CT47B1 (86% identical), and 1 more.